TMEM25 (transmembrane protein 25)
Description:
In neurons, modulates the degradation of NMDA receptor GRIN2B subunit. Plays a role in the regulation of neuronal excitability.
Synonyms: FLJ14399
Tractability: Antibody: UniProt places it where antibodies can reach, with high confidence; UniProt predicts a signal peptide or a membrane-spanning region; its Gene Ontology location is reachable by antibodies, with medium confidence.
Gene: Protein-coding gene on chromosome 11 (118,531,041 to 118,547,280, forward strand). Ensembl gene ENSG00000149582.
Subcellular location: Cell membrane (Isoform 1); Cell membrane (Isoform 4); Secreted (Isoform 2); Secreted (Isoform 3); Late endosome; Lysosome
Subcellular location (Human Protein Atlas): Golgi apparatus; Vesicles
Gene Ontology:
Molecular function: protein binding
Biological process: negative regulation of excitatory postsynaptic potential; regulation of protein stability
Cellular component: late endosome; lysosome; extracellular region; plasma membrane
Genetic constraint (gnomAD): Loss-of-function variants: 36 observed, 36.84 expected, observed/expected ratio (o/e) 0.98, 90% interval 0.75 to 1.29. The upper end of that interval is the gene's LOEUF score, 1.29, which puts it in group 5 of 6, group 1 being the genes least tolerant of losing a copy. Missense variants: 444 observed, 485.86 expected, observed/expected ratio (o/e) 0.91, 90% interval 0.85 to 0.99. Synonymous variants: 197 observed, 208.94 expected, observed/expected ratio (o/e) 0.94, 90% interval 0.84 to 1.06.
Homologues: Orthologues: macaque TMEM25 (93% identical), chimpanzee TMEM25 (91% identical), dog TMEM25 (91% identical), mouse Tmem25 (91% identical), pig TMEM25 (90% identical), guinea pig TMEM25 (90% identical), rat Tmem25 (83% identical), rabbit TMEM25 (66% identical). Paralogues in human: SIGLEC1 (30% identical), SIGLEC10 (17% identical), SIGLEC6 (17% identical), SIGLEC5 (17% identical), SIGLEC7 (16% identical), SIGLEC11 (15% identical), SIGLEC12 (15% identical), SIGLEC8 (15% identical), SIGLEC9 (15% identical), CD22 (15% identical), MAG (12% identical), CD33 (10% identical), and 4 more.
Diseases named in the same sentence as TMEM25 in open-access papers:
TMEM25 is named in the same sentence as 15 diseases in open-access papers, as found by Europe PMC text mining. Sharing a sentence is not in itself a finding about the gene and the disease. The quoted sentences say what the papers report.
breast carcinoma (7 papers, 2015 to 2025). "One of the top hypermethylated genes, TMEM25, has been implicated in colorectal cancer and is correlated with favorable prognosis in breast cancer, confirming a potential widespread tumor suppressor role for TMEM25." (PMID 25631659, 2015). "Reduced Tmem25 expression in breast cancer has been correlated with a better response to chemotherapy." (PMID 38139000, 2023). "The expression of Meis1, along with transmembrane protein 25 (Tmem25) and Reps2, has been suggested to be a marker for breast cancer prognosis." (PMID 33402862, 2020). "High expression of Meis1, Tmem25, and Reps2 is a determining factor for evaluating the probability of relapse and survival of breast cancer." (PMID 33402862, 2020). "Interestingly, in breast cancers, TMEM25 mRNA levels were decreased most dramatically in TNBCs compared with normal mammary tissues." (PMID 37095176, 2023). "Only two studies have examined Tmem25 expression in colon and breast cancer." (PMID 38139000, 2023).
colorectal cancer (7 papers, 2015 to 2024). A primary or metastatic malignant neoplasm that affects the colon or rectum. "In colorectal cancer, elevated methylation of TMEM25 exhibits an inverse correlation with its expression." (PMID 38189809, 2024). "One clinical study showed that Tmem25 expression was decreased in colorectal cancer; therefore, Tmem25 has been considered as a therapeutic target." (PMID 38139000, 2023). "However, the down-regulation of TMEM25 is colorectal cancer-related, which needs further studies to clarify the molecular mechanism of TMEM25 in sheep." (PMID 36032143, 2022).
lung carcinoma (2 papers, 2024 to 2025). "TMEMs are a family of proteins that have been found to be expressed in various cancers, including lymphomas (TMEM176), colorectal (TMEM25), hepatic (TMEM7), and lung cancers (TMEM48)." (PMID 38974022, 2024).
brain tumors (1 paper, 2021). "TMEM25 encodes a transmembrane protein that is expressed in multiple brain regions, including the cerebellar cortex and hippocampus, as well as in neuroblastoma and brain tumors, and may be involved in the promotion of axon growth and the regulation of cell migration." (PMID 31477794, 2021).
cyst (1 paper, 2024). A sac-like closed membranous structure that may be empty or contain fluid or amorphous material. "The significance of TMEM25 in cell polarity control is also demonstrated by an aberrant cyst formation in TMEM25-depleted MDCK cells in 3D culture." (PMID 38177906, 2024). "Thus, TMEM25 appears to contribute to apico-basal polarization during cyst development." (PMID 38177906, 2024).
kidney cancer (1 paper, 2024). Primary or metastatic malignant neoplasm involving the kidney. "A significant reduction in TMEM25 expression was observed among the mutation groups of BAP1, UNC80, EYS, SETD2 and XIRP, compared with the wild group, as BAP1 and SETD2 are commonly occurring mutation types in kidney cancer and have poor prognosis." (PMID 38189809, 2024).
lung adenocarcinoma (1 paper, 2024). A carcinoma that arises from the lung and is characterized by the presence of malignant glandular epithelial cells. "Specifically, TMEM25 exhibited high expression levels in breast invasive carcinoma (BRCA) and lung adenocarcinoma (LUAD)." (PMID 38189809, 2024).
tumor (13 papers, 2015 to 2024). "Additionally, they explore the correlations between TMEM25 expression and DNA methylation, gene mutations, immune cell infiltration, and drug sensitivity within this specific tumor context." (PMID 38189809, 2024). "We confirmed that the phosphorylation levels of STAT3 in primary tumor tissues from mice injected with wild-type TMEM25-encoded AAV were significantly lower than those from mice injected with control AAV, or TMEM25-R326W or TMEM25-L338F encoded AAV by immunoblotting assay." (PMID 37095176, 2023). "Deletion of TMEM25 significantly promoted the growth of TNBC cells in vitro and in vivo, whereas overexpression of TMEM25 displayed opposite effects, suggesting that TMEM25 plays a crucial role in tumor progression." (PMID 38532948, 2024). "Strikingly, knockout of TMEM25 drastically promoted the tumor growth and lung metastasis, whereas overexpression of TMEM25 markedly suppressed the tumor growth and lung metastasis." (PMID 37095176, 2023). "Accordingly, knockout of TMEM25 significantly increased the xenograft tumor growth of MDA-MB-231 cells in nude mice whereas overexpression of TMEM25 inhibited the tumor growth." (PMID 37095176, 2023). "It is noteworthy that the normalized lung metastasis to primary tumor burden was also increased by knockout of TMEM25 and decreased by overexpression of TMEM25." (PMID 37095176, 2023). "Members of this family can act as both oncogenes, such as TMEM45A and TMEM205, or tumor suppressors, such as TMEM25 and TMEM7." (PMID 36077735, 2022). "Another study revealed that TMEM25 expression in the tumor tissues was lower than the one in normal healthy tissues in 50% of tumor samples in human breast tumor biopsies." (PMID 30574087, 2018). "TMEM25 mRNA expression was significantly decreased in 68% of tumor tissues in comparison to corresponding normal tissues." (PMID 30574087, 2018). "This downregulation has been correlated with the hypermethylation of a specific CpG site in the 5′ UTR region of TMEM25 gene in a high proportion of tumor samples." (PMID 30574087, 2018). "Notably, the tumor growth and lung metastasis were evident upon TMEM25 knockout, and overexpression of TMEM25 regressed these effects indicating that TMEM25 displays inhibitory activity on spontaneous TNBC in mice." (PMID 38532948, 2024). "Importantly, the transcript levels of TMEM25 were significantly low in tumor tissues derived from TNBC patients in comparison with adjacent normal counterparts." (PMID 38532948, 2024). "We next further examined the effect of providing wild-type TMEM25 in a patient-derived xenograft (PDX) TNBC tumor model, and found that supply of TMEM25 by AAV could also significantly inhibit PDX TNBC tumor growth." (PMID 37095176, 2023). "Furthermore, knockdown of STAT3 drastically suppressed xenograft tumor growth of both wild-type and TMEM25 −/− MDA-MB-231 cells in nude mice to a similar level." (PMID 37095176, 2023). "All together these findings suggest that TMEM25 may be used as a tumor biomarker of favorable prognosis." (PMID 30574087, 2018). "Furthermore, some of these proteins act as tumor suppressors (e.g., TMEM25, TMEM7) while others act as pro-oncogenes (e.g., TMEM158, TMEM14A...)." (PMID 30574087, 2018). "Our study also demonstrates a potential of TMEM25 for targeted therapy of TNBC, and suggests that clinical mutations of TMEM25 identified in other types of cancer may be able to trigger monomeric-EGFR/STAT3 signaling to promote tumor progression as well." (PMID 37095176, 2023). "Overall, it is a well‐planned and refined study that comprehensively demonstrated TMEM25 as a tumor suppressor protein that prevents the interaction of monomeric EGFR with STAT3 and thereby suppresses STAT3 phosphorylation and tumor progression." (PMID 38532948, 2024). "Some of TMEM proteins act as tumor suppressors such as TMEM7, TMEM25, TMEM97, and TMEM176A; while a large number of them act as oncogenes such as TMEM14A and TMEM158." (PMID 37335919, 2023).
tumor (continued). "In this study, we identify TMEM25 as an EGFR binding protein to prevent monomeric EGFR-mediated phosphorylation of STAT3 in the basal state, therefore functioning as a tumor suppressor to inhibit TNBC progression." (PMID 37095176, 2023). "The other TSGs, such as SEPP1, TMEM25, XPNPEP2, and G6PC, have been reported to play a role in tumor suppression." (PMID 32774369, 2020). "Strikingly, injection with wild-type TMEM25, but not TMEM25-R326W or TMEM25-L338F, encoded AAV showed significant inhibitory effect on the spontaneous TNBC tumor growth in MMTV-PyMT transgenic mice." (PMID 37095176, 2023). "Hence, these results suggested that loss of TMEM25 promotes cell growth or survival via activating EGFR/STAT3 signaling pathway, which may play a pivotal role in TNBC development, especially for the cells inside a tumor where with limited supply of growth factors." (PMID 37095176, 2023). "As in previous studies, TMEM25 shows downregulation in tumor samples as compared to the normal samples and has been proven to act as a tumor suppressor in CRC." (PMID 34253750, 2021).
cancer (8 papers, 2015 to 2024). A tumor composed of atypical neoplastic, often pleomorphic cells that invade other tissues. "Out of the 224 cancer samples, missense substitutions emerged as the predominant type of TMEM25 mutation, constituting a significant portion of 106 cases (47.32%)." (PMID 38189809, 2024). "COSMIC website shows the types of mutations in TMEM25 in different cancers." (PMID 38189809, 2024). "Therefore, it will be necessary to assess the correlation between TMEM25 and overall survival rates of cancer patients by distinguishing these mutations from expression level changes." (PMID 37095176, 2023). "This study presents a comprehensive examination of TMEM25 expression across various cancers, accomplished through a pancancer analysis." (PMID 38189809, 2024). "This revelation underscores the intricate interplay between TMEM25 and these genes, potentially highlighting shared molecular pathways or biological processes relevant to cancer." (PMID 38189809, 2024). "These revelations collectively hint at TMEM25’s potential as both a prognostic biomarker and a target for therapeutic interventions in cancer." (PMID 38189809, 2024). "Seven genes are hypermethylated in ten cancer sites: six encoding zinc finger transcription factors (ZNF135, ZNF354C, ZNF415, ZNF542, ZNF671, ZSCAN18) and one encoding a transmembrane protein (TMEM25)." (PMID 25631659, 2015). "Since TMEM25 is a regulator of claudin assembly as demonstrated in the present study, its low expression probably leads to an aberrant regulation of TJ development and contributes to cancer progression." (PMID 38177906, 2024). "Indeed, as part of the TMEM protein family, TMEM25 is also of great importance in the field of cancer, where it plays an active role in the process of cancer development and progression." (PMID 38189809, 2024). "The outcomes of this pan-cancer TMEM25 analysis, derived from the TIMER online platform." (PMID 38189809, 2024). "In addition, previous studies have shown that several TSGs had significantly higher methylation levels in cancer, such as CBFA2T3 and TMEM25." (PMID 32774369, 2020). "EGFRV948R transfection retained STAT3 phosphorylation in EGFR−/−, TMEM25−/− TNBC cells, strongly suggesting that EGFR can phosphorylate STAT3 in the monomeric form in the absence of TMEM25 and thereby relays sustainable proliferative signals to cancer cells to provide the growth advantage." (PMID 38532948, 2024).
adenocarcinoma (1 paper, 2024). A common cancer characterized by the presence of malignant glandular cells. "Indeed, depletion of TMEM25 induces an abnormal cyst formation in 3D culture of MDCK cells, indicative of an impaired cell polarity; and TJ structure alteration and subsequent impaired polarization are considered to result in a multitude of diseases, especially adenocarcinoma of various organs." (PMID 38177906, 2024).
TMEM25 also shares sentences with these, for which no sentence is quoted: lymphoma (2 papers); triple-negative breast carcinoma (2); colon cancer (1); neuroblastoma (1); renal clear cell carcinoma (1).